JAK2 (Janus kinase 2)
Diseases named in the same sentence as JAK2 in open-access papers (continued):
Sharing a sentence is not in itself a finding about the gene and the disease.
renal fibrosis (24 papers, 2013 to 2025). A final common manifestation of a wide variety of chronic kidney diseases characterized by glomerulosclerosis and tubulointerstitial fibrosis. "The purpose of this study was to investigate the potential effect of anti-dsDNA IgG on the regulation of SOCS1 signals and also the molecular mechanism underlying SOCS1-KIR and JAK2/STAT1 interaction in the pathogenesis of renal fibrosis." (PMID 28620377, 2017). "Activation of STAT3 is associated with many forms of renal injury and the JAK2/STAT3 pathway has been implicated in the progression of renal fibrosis in several models of renal disease." (PMID 24167575, 2013). "Activation of Jak2-Stat3 has also been implicated in renal fibrosis." (PMID 26872211, 2016). "Chronic treatment with silymarin nanoliposomes effectively ameliorated inflammation, OS, and renal fibrosis via inhibiting JAK2/STAT3/suppressor of cytokine signaling 1 and TGF‐β/Smad signaling pathways in diabetic rats with STZ‐induced kidney injury." (PMID 41019174, 2025). "The association of JAK2 with cardiac fibrosis, renal fibrosis, IPF, and RA-UIP suggests that JAK2 plays an important role in the regulation of tissue fibrosis." (PMID 37194022, 2023). "In conclusion, long-term administration of ISO at all three dosages (10, 20, and 40 mg/kg) effectively improved STZ-induced acute renal injuries in DN model rats via improving renal fibrosis, oxidative stress, and inhibiting JAK2/STAT3 signaling pathway." (PMID 34784849, 2021). "SOCS1 participates in renal fibrosis by downregulating JAK2/STAT1-mediated cytokine signaling in LN." (PMID 30214448, 2018). "Suppressor of cytokine signaling 1 (SOCS1) participates in renal fibrosis by downregulating Janus kinase 2 (JAK2)/signal transducer and activator of transcription 1 (STAT1)-mediated cytokine signaling." (PMID 28620377, 2017). "Its renoprotective activities are via the RhoA/Rho‐associated coiled‐coil‐containing kinase signaling pathway, suppressing renal fibrosis in HG‐induced glomerular MCs, upregulating Janus Kinase‐2 (JAK2)/STAT3 and Nrf‐2/HO‐1, TGF‐β1/Smad/ECM, and TGF‐β1/CTGF/ECM signaling cascades." (PMID 41019174, 2025). "Similarly, the combination of Astragalus membranaceus and Panax notoginseng synergistically alleviates renal fibrosis via the HIF-1α/JAK2/STAT3 axis." (PMID 41487503, 2025). "And promotes renal fibrosis by regulating inflammatory signaling pathways such as JAK2/STAT3." (PMID 39705287, 2024). "In the RTN3 KO mouse model, we also found that deletion of RTN3 can activate the IGF2–Janus kinase 2 (JAK2) pathway, which may further lead to chronic kidney disease and renal fibrosis." (PMID 36925557, 2023). "In conclusion, this experimental study shows that β-elemene reduces renal fibrosis by targeting JAK2/STAT3, Smad3, and Myd88 signaling factors and may serve as a potent inhibitor of STAT3 and Smad3 in the future." (PMID 35628363, 2022). "In conclusion, our data suggest that SK may effectively inhibit renal fibroblast activation and renal fibrosis in UUO mice by regulating the JAK2/STAT3 signaling pathway." (PMID 33407391, 2021). "Experimental evidence suggests that inhibition of JAK/STAT (in particular, JAK2/STAT3) may suppress renal fibrosis and thereby protect renal function." (PMID 34335747, 2021). "In conclusion, ISO at all three dosages could efficiently improve the renal injury induced by STZ via ameliorating renal fibrosis, oxidative stress, and inhibiting JAK2/STAT3 signaling pathways in the DN rats." (PMID 34784849, 2021). "Furthermore, long-term administration of ISO could ameliorate excessive oxidation stress, down-regulate the expression levels of renal fibrosis- and inflammation-related factors, as well as inhibit the JAK2/STAT3 signaling pathway." (PMID 34784849, 2021). "Thus, JAK2/STAT3 could be a direct therapeutic target of SK for renal fibrosis." (PMID 33407391, 2021).
renal fibrosis (continued). "Furthermore, a chronic study in DN model rats revealed that long-term treatment of ISO could improve the diabetic characteristics and renal functions in acute DN rats through ameliorating renal fibrosis, oxidative stress, and inhibiting JAK2/STAT3 signaling pathways." (PMID 34784849, 2021). "In the present study, on the 14th day after obstruction, the mRNA levels of α-SMA, JAK2 and STAT3 were significantly increased with increased renal fibrosis degree." (PMID 33407391, 2021). "Several previous publications have highlighted that SKI retarded renal fibrosis by inhibiting levels of interleukin-6, interleukin-1β, and TNF-α and modulating TGF-β1/Smad3 and JAK2/STAT3 signaling pathways." (PMID 35002735, 2021). "Our results showed that SK reduced extracellular matrix (ECM) and α-smooth muscle actin (α-SMA) expression both in vitro and in vivo and attenuated renal fibrosis and the pathological lesion degree after UUO, suppressing JAK2/STAT3 activation." (PMID 33407391, 2021). "Since MMP-2 is a target gene of STAT3, JAK2/STAT3 blockade reduced MMP-2 expression and renal fibrosis in the developing kidney with obstruction." (PMID 31846485, 2019). "Previous studies have shown that signaling factors such as JAK2/STAT3, Smad3, and Myd88 play a regulatory role in renal fibrosis, and β-elemene is a plant-derived sesquiterpenoid organic compound that has been shown to have anti-inflammatory, anti-cancer, and immunomodulatory effects." (PMID 35628363, 2022). "On the contrary, inhibition of JAK2 and Stat3 in unilateral ureteral obstruction (UUO)-related renal fibrosis could abrogate the myofibroblast phenotypic transition of renal cells and attenuate renal fibrosis to improve renal function." (PMID 33138205, 2020). "The increased expression of JAK2 in podocytes and other glomerular and tubulointerstitial cells in Akita diabetic podocyte JAK2 mice further leads to DKD-related pathological changes, such as albuminuria, mesangial dilatation, glomerular sclerosis, and renal fibrosis." (PMID 37635867, 2023). "Mechanistically, several preliminary studies have revealed that SKI alleviated CKD and renal fibrosis by inhibiting pro-inflammatory cytokines such as interleukin-6, interleukin-1β, and tumor necrosis factor-α (TNF-α) expression and modulating TGF-β1/Smad3 and JAK2/STAT3 signaling pathways." (PMID 35002735, 2021). "In conclusion, anti-dsDNA IgG downregulates SOCS1 expression, activates JAK2/STAT1 signals, and contributes to renal fibrosis; its peptide blockade may restore the SOCS1 inhibitory effect on the production of profibrotic cytokine, and finally ameliorate renal fibrosis in LN." (PMID 28620377, 2017).
atopic dermatitis (23 papers, 2016 to 2026). "Moreover, the miR-375-3p controls Janus kinase 2 (JAK2) signaling which has been linked to atopic dermatitis." (PMID 37965316, 2023). "For example, the effectiveness of JAK2 inhibitors has been confirmed in chronic inflammatory skin diseases, such as atopic dermatitis, vitiligo, and alopecia." (PMID 39335596, 2024). "None of the inflammatory skin diseases is characterized by an increased expression of JAK2; phosphorylated JAK2 was overexpressed in atopic dermatitis and pyoderma gangrenosum." (PMID 37624299, 2023). "Recently, inhibition of IL-5 signaling via JAK2 has been reported to be effective in bronchial asthma and atopic dermatitis." (PMID 37000107, 2023). "6b (Baricitinib) is a JAK1 and JAK2 inhibitor developed by Eli Lilly and Company for the treatment of RA, atopic dermatitis, and systemic lupus erythematosus." (PMID 36770611, 2023). "The appearance of side effects in patients treated with dupilumab for atopic dermatitis, already extensively described in the literature, has made it possible to demonstrate the efficacy of upadacitinib, a JAK2 inhibitor, in a case of atopic dermatitis severe and AKC." (PMID 37658939, 2023). "Of note, it was found that JAK2 could modulate DC differentiation and that the inhibition of JAK2 could suppress inflammatory dendritic epidermal cell development and function in atopic dermatitis." (PMID 35710633, 2022). "JAK2 inhibitors have been identified as effective reagents for the treatment of atopic dermatitis." (PMID 33917914, 2021). "Isoliquiritin downregulates the JAK/STAT signaling pathway by inhibiting the phosphorylation of JAK2, STAT1, STAT3, and STAT5, thereby regulating immune and inflammation responses and contributing to the treatment of atopic dermatitis." (PMID 40657637, 2025). "Ruxolitinib 1.5% cream is a selective topical JAK1 and JAK2 inhibitor, which has recently been approved by EMA and MHRA for treating non-segmental vitiligo, while being FDA-approved for both vitiligo and atopic dermatitis." (PMID 40192197, 2025). "The anti-inflammatory properties of CBD, combined with its specific inhibition of JAK2, warrant further investigation into the use of CBD for treating atopic dermatitis and other immune-mediated conditions, such as alopecia." (PMID 39335596, 2024). "6g is a potent, orally available, pan-JAK inhibitor with IC50 values of 2.8, 2.6, 13, and 58 nM for JAK1, JAK2, JAK3, and Tyk2, respectively, which was approved for the treatment of atopic dermatitis in Japan." (PMID 36770611, 2023).
mastitis (19 papers, 2015 to 2025). Inflammation of breast tissue during lactation or postpartum due to an obstructed duct or infection. "Further study is highly recommended to find out the specific variants in SOCS3 that interact with STAT5 and JAK2 during mastitis development and milk production in dairy cattle." (PMID 33202860, 2020). "It was reported that JAK2 gene was associated with bovine mastitis resistance." (PMID 41234403, 2025). "SYK and PTK2B may be involved in the SYK/PTK2B/AKT1/JAK2 pathway in bMECs that stimulates IL-8 secretion and recruits neutrophils to kill pathogenic microorganisms, resulting in the resistance to mastitis inflammation." (PMID 31447828, 2019). "Previous research has mostly concentrated on the impact of SNPs within the JAK2 gene on cattle and sheep traits, such as growth, milk production, and mastitis resistance." (PMID 38998106, 2024). "JAK2 also has a role in mastitis and milk production in cows providing a possible use elsewhere in dairy farming." (PMID 39817173, 2024). "JAk2 and STAT5, two key players in the immune cascade response, are associated with bovine mastitis susceptibility." (PMID 36672605, 2022). "We suggest that further studies should be carried on epigenetic modifications (DNA methylation) of the JAK2 gene in dairy cattle with clinical mastitis in a larger population." (PMID 35011171, 2021). "The activation of JAK2 and STATs genes has a critical role in milk production and mastitis resistance." (PMID 33202860, 2020). "In previous genome-wide association studies (GWAS), a number of candidate genes (TRAPPC9, mTORC1, JAK2 and STAT5A) were observed to be associated with mastitis-related traits such as SCC." (PMID 32944235, 2020). "The upregulation of SOCS3 in bovine mammary epithelial cells inhibits the activation of JAK2 and STATs genes, which promotes mastitis development and reduces the lactational performance of dairy cattle." (PMID 33202860, 2020). "JAK2 and STAT5, two key players in the immune response, are associated with cow mastitis susceptibility." (PMID 31447828, 2019). "It has been proposed that sinomenine hydrochloride may have therapeutic effects on plasma cell mastitis based on its anti–inflammatory and immunomodulatory properties, which are exerted through the downregulation of the IL–6/JAK2/STAT–3 pathway." (PMID 40005889, 2025). "In addition, abnormal DNA methylation at the CpG site in the 1 kb promoter region of JAK2, STAT5A and CD4 genes caused by mastitis can be used as a potential epigenetic marker to estimate mastitis susceptibility in dairy cows." (PMID 37569258, 2023). "The presence of six active TFs in the CpG island of the JAK2 gene in the present study shows that these TFs could have a potential role in gene activation and silencing; thus, they can play important roles in mastitis resistance." (PMID 35011171, 2021). "The variable DNA methylation levels of CpG sites in the JAK2 promoter region reveal that methylation at these sites could be a potential epigenetic marker for mastitis resistance." (PMID 35011171, 2021). "The interactions of polymorphisms in JAK2 with bovine mastitis resistance phenotypic traits (IL-17, IL-6, IL-4, IFN-γ, SCS, and SCC) show that JAK2 might be considered a useful marker in bovine mastitis resistance strategies." (PMID 33202860, 2020). "Recently, the JAK2, STATs, and inhibitors of the JAK-STAT pathway, especially cytokine signaling suppressors (SOCSs), have been reported to be associated with milk production and mastitis-resistance phenotypic traits in dairy cattle." (PMID 33202860, 2020). "The genes correlated with downregulated SNORA1 (e.g., JAK2 and IL6R) have been shown to stimulate inflammation during subclinical mastitis as discussed in several reviews." (PMID 40936092, 2025).
mastitis (continued). "The CpG islands in the promoter regions of JAK2 and STAT5A gene were found to be hypomethylated, resulting in increased gene expression in cows with mastitis compared to healthy controls; the opposite was seen with the CD4 gene." (PMID 39045327, 2024). "A SNP in the JAK2 gene was observed to affect SCC values significantly, with significant dominant effects observed in the fat percentage (p < 0.05), suggesting that these could be used as potential epigenetic markers for the prediction of mastitis susceptibility in dairy cattle." (PMID 39045327, 2024). "The CpG islands in the promoter regions of the JAK2 and the STAT5A revealed hypo-methylation levels and higher gene expression in cows with mastitis compared to the healthy control, and vice versa in those with the CD4 gene." (PMID 35011171, 2021). "The evaluation of DNA methylation in promoter regions of JAK2 and STAT5A revealed hypo-methylation levels of CpG sites and higher gene expression in cows diagnosed with mastitis as compared to the healthy control, and vice versa in those with CD4." (PMID 35011171, 2021). "Moreover, in cows diagnosed with mastitis, the methylation of the STAT5A promoter was lowest compared with JAK2 and CD4, about 9–11%, but the expression of STAT5A still changed significantly." (PMID 40214477, 2025). "Although some studies have shown that the IL-6/JAK2/STAT3 signaling pathway is related to non-puerperal mastitis, such reports are few." (PMID 37817809, 2023). "Findings of the current study inferred that aberrant DNA methylation in the CpG sites at the 1 kb promoter region in JAK2, STAT5A, and CD4 genes due to mastitis in cows can be used as potential epigenetic markers to estimate bovine mastitis susceptibility in dairy cattle." (PMID 35011171, 2021). "Furthermore, it is suggested that the interactive mechanism of SOCS3, STATs, and JAK2, STAT5A, and STAT5B during milk production and mastitis development should be considered in future rodent-knockout research models." (PMID 33202860, 2020).
type 2 diabetes mellitus (19 papers, 2012 to 2025). A type of diabetes mellitus that is characterized by insulin resistance or desensitization and increased blood glucose levels. "The results of phase II clinical trials on baricitinib (another JAK1/JAK2 inhibitor) indicated reduced urinary ACR by 40% over 24 weeks in patients with Type 2 diabetes and DKD." (PMID 34202668, 2021). "In Sawano cells and normal HEEs, a decrease of LSR induced by leptin and an increase of LSR induced by adiponectin and the drugs for type 2 diabetes metformin and berberine were observed via distinct signaling pathways including JAK2/STAT." (PMID 27036040, 2016).
Alzheimer disease (18 papers, 2015 to 2026). A progressive, neurodegenerative disease characterized by loss of function and death of nerve cells in several areas of the brain leading to loss of cognitive function such as memory and language. "Inactivation of JAK2 can cause memory loss in Alzheimer's disease." (PMID 34368281, 2021). "Baricitinib, another FDA-approved JAKi, blocks interferon responses in Alzheimer’s disease while the JAK2 inhibitor AZD1480 lessens neuroinflammation and neurodegeneration in Parkinson’s disease." (PMID 39508990, 2025). "A report has indicated that age- and disease-dependent deterioration in the Jak2/STAT3 axis plays a critical role in the pathogenesis of Alzheimer's disease." (PMID 33228717, 2020). "With their innate physiological roles as well as being direct interacting partners (guilt-by-association) to already known AD genes (JAK2 and PECAM1) increases the chances of the two genes (CSF1R and GAB1) as novel candidate genes for Alzheimer’s disease." (PMID 26784894, 2016). "In summary, this study we have also identified important genes (NRG1, NEDD9, IRF5, IFI35, STAT1, STAT2, JAK2, IL3RA), and alterations in biological processes and pathways that may be associated with Alzheimer’s Disease." (PMID 34484988, 2021). "JAK2/STAT3 axis targeting is suggested in Alzheimer's disease." (PMID 33585010, 2020). "Furthermore, plasma β-amyloid (40/42) levels are increased in Alzheimer’s disease patients with hyperglycemia and they exacerbate hepatic insulin resistance by activating Janus kinase-2 signaling in the liver." (PMID 25755673, 2015). "JAK2 and STAT3 are key proteins in this pathway, playing an important role in multiple CNS pathologies, such as Alzheimer's disease, Parkinson's disease, and cerebral ischemic disorders." (PMID 36627822, 2023). "In an Alzheimer’s disease model, blocking BDNF/TrkB neurotrophic signaling up-regulated inflammatory factors and activated the JAK2/STAT3 pathway, therefore up-regulating CEBPB." (PMID 35204186, 2022). "Moreover, WGX50 also inhibits neuroinflammation induced by the amyloid-beta (Aβ) peptide in microglia via 7nAChR activation of the JAK2/STAT 3 and PI3K/AKT pathways, which may be a hopeful therapeutic molecular compound against Alzheimer’s Disease (AD)." (PMID 37978379, 2023).